RNU6-381P (RNA, U6 small nuclear 381, pseudogene)
Gene: Small nuclear RNA gene on chromosome 5 (44,066,624 to 44,066,731, reverse strand). Ensembl gene ENSG00000212561.
Homologues: Orthologues: chimpanzee U6 (98% identical), macaque U6 (91% identical). Paralogues in human: RNU6-742P (85% identical), RNU6-83P (83% identical), RNU6-85P (83% identical), RNU6-116P (82% identical), RNU6-39P (82% identical), RNU6-1145P (81% identical), RNU6-1227P (81% identical), RNU6-151P (81% identical), RNU6-266P (81% identical), RNU6-33P (81% identical), RNU6-38P (81% identical), RNU6-413P (81% identical), and 1284 more.